STAT1 (signal transducer and activator of transcription 1)
Diseases named in the same sentence as STAT1 in open-access papers (continued):
Sharing a sentence is not in itself a finding about the gene and the disease.
pulmonary fibrosis (22 papers, 2007 to 2024). Chronic progressive interstitial lung disorder characterized by the replacement of the lung tissue by connective tissue, leading to progressive dyspnea, respiratory failure, or right heart failure. "Stat1 KO mice are also susceptible to bleomycin-induced lung fibrosis with heightened proliferative responses to growth factors such as platelet-derived growth factor (PDGF) and epidermal growth factor (EGF)." (PMID 33022979, 2020). "We previously reported that Stat1−/− mice are susceptible to lung fibrosis caused by oropharyngeal aspiration of bleomycin or by co-exposure to MWCNTs and ovalbumin allergen." (PMID 28716119, 2017). "The susceptibility of Stat1−/− mice to pulmonary fibrosis is consistent with the well-established function of STAT1 as a primary growth inhibitory signaling pathway for interferons." (PMID 28716119, 2017). "Another study in rats suggested that STAT1 inhibits bleomycin-induced lung fibrosis, while reduced SOCS1 expression has been linked to pulmonary fibrosis in patients and in animal models." (PMID 27834824, 2016). "In this study, we use gp130 mutant mice with either deregulated Stat1/3 or Erk1/2-signalling to assess susceptibility to bleomycin administration as a widely used model that recapitulates epithelial injury-induced lung fibrosis." (PMID 22684844, 2012). "We previously showed that V2O5 activates STAT1 in lung fibroblasts and mice deficient in STAT1 are susceptible to pulmonary fibrosis." (PMID 17459161, 2007). "Mice deficient in IP10, and in STAT1, displayed enhanced susceptibility to pulmonary fibrosis." (PMID 23915349, 2013). "Additionally, STAT1−/− mice demonstrated a greater susceptibility to chemically induced pulmonary fibrosis via bleomycin treatment." (PMID 20386712, 2010). "In a bleomycin-induced pulmonary fibrosis mice model, IL-35 activated STAT1 and STAT4, which in turn suppressed DNA enrichment of STAT3 and inhibited the fibrosis process." (PMID 38641226, 2024). "Modulating STAT1 acetylation represents a promising strategy for the treatment of pulmonary fibrosis, as shown by the results of our present study." (PMID 38641226, 2024). "The downregulation of miR-129-5p can significantly promote STAT1 gene expression in macrophages to inhibit pulmonary fibrosis in rats." (PMID 38641226, 2024). "From a clinical perspective, patients with idiopathic pulmonary fibrosis have lower levels of STAT1 protein than normal individuals." (PMID 33022979, 2020). "Studies in mouse models of bleomycin-induced lung fibrosis and CCl4-induced liver fibrosis suggested a protective role for STAT1." (PMID 27834824, 2016). "All of these studies clearly indicate that STAT-1 plays a protective role in limiting mesenchymal cell survival and resolving lung fibrosis." (PMID 20738867, 2010). "M2 macrophages can carry miR-129-5p to pulmonary interstitial fibroblasts and inhibit STAT1 gene expression, which may lead to the proliferation of fibroblasts and promote pulmonary fibrosis." (PMID 38641226, 2024). "To verify whether acetylation of Stat1 plays as a potential drug target in silica-induced pulmonary fibrosis, we performed GGA administration in this study." (PMID 38641226, 2024). "STAT1 antisense oligonucleotides (ASON) could inhibit the secretion of TNF-α and ICAM-1 in alveolar macrophages (AMs), and STAT1 could become a target of treating pulmonary fibrosis." (PMID 33072088, 2020). "STAT1 was shown to be an important controller of tumor formation in several types of cancers including lung, colon, pancreatic and brain cancers and its role in cell proliferation has been studied in the context of pulmonary fibrosis." (PMID 20386712, 2010). "Regarding gp130 activation by IL-31, there is not much evidence of its relationship with ILDs, but one study in a mouse pulmonary fibrosis model found that IL-31 signals through STAT1 activation, and may constitute a possible pathway of mouse pulmonary fibrosis." (PMID 34207510, 2021).
pulmonary fibrosis (continued). "Furthermore, the development of novel agonists that activate STAT-1 may prove beneficial for managing or treating pulmonary fibrosis." (PMID 20738867, 2010). "However, STAT-1-/- mice develop more severe pulmonary fibrosis after lung injury with bleomycin." (PMID 20738867, 2010). "In bleomycin-induced pulmonary fibrosis mice model, HDAC3 promoted EMT, inflammation, and pulmonary fibrosis development by activating STAT1 signaling." (PMID 38641226, 2024). "In research about pulmonary fibrosis, FTH1 is involved in ferroptosis, whereas P62 and STAT1 are involved in autophagy." (PMID 38147026, 2023). "In addition to the abrogation of gene expression noted, Stat1-/- young mice infected with the most severe MA15 variant were unable to clear the infection, accompanied by elevation of neutrophils, eosinophils, and macrophages, acute respiratory distress, and pulmonary fibrosis resulting in death." (PMID 38107402, 2023). "Unlike STAT3, recent studies using knockout mice showed that STAT1 and STAT5 play key roles in promoting liver and lung fibrosis after injury." (PMID 37569586, 2023). "The study aimed to explore the effect of total flavonoids of Oxytropis falcata Bunge (FOFB) on the expression of p-JAK1/p-STAT1 and SOCS3 proteins in idiopathic pulmonary fibrosis (IPF)." (PMID 32908556, 2020). "To investigate the mechanism by which IL-27 acts in pulmonary fibrosis, we determined JAK, STAT1, STAT3, STAT5, and SOCS3 protein levels as well as STAT1, STAT3, and STAT5 phosphorylation levels using Western blot analysis." (PMID 25888222, 2015). "In contrast to deletion of STAT-1 or STAT-6, STAT-3 deletion in mice is lethal and therefore little is known about the role of STAT-3 in lung fibrosis." (PMID 20738867, 2010). "Although there is no published work of STAT1 in silicosis, the study of STAT1 in pulmonary fibrosis is well described." (PMID 38641226, 2024). "FOFB has a therapeutic effect on inflammation-mediated idiopathic pulmonary fibrosis, and its mechanism may be to inhibit the expression of p-JAK1 and p-STAT1 inflammatory proteins by upregulating the expression of SOCS3." (PMID 32908556, 2020). "Thus, STAT1 and STAT3 appear to have divergent roles in the physiopathology of DM-induced lung fibrosis." (PMID 27834824, 2016).
esophageal squamous cell carcinoma (21 papers, 2013 to 2025). Esophageal squamous cell carcinoma (ESCC) is a type of esophageal carcinoma (EC) that can affect any part of the esophagus, but is usually located in the upper or middle third. "In addition, the loss of STAT1 has been related to the tumorigenesis of several cancer types, and is implicated as a tumor suppressor in esophageal squamous cell carcinoma." (PMID 31014274, 2019). "A study published in Cell Reports revealed the important antitumor function of the deubiquitinating enzyme OTUB2 in oral and esophageal squamous cell carcinomas by promoting phosphorylation and dimer formation of the transcription factor STAT1." (PMID 37573347, 2023). "Previous research revealed that STAT1 acted as a tumor suppressor in esophageal squamous cell carcinoma and that constitutively activated STAT1 decreased cell growth and induced apoptosis." (PMID 33391406, 2021). "For example, a recent study showed that STAT1β can enhance STAT1 function by protecting STAT1α from degradation in esophageal squamous cell carcinoma." (PMID 32867271, 2020). "We recently reported that STAT1 plays a tumor suppressor role, and ERK was inversely correlation with STAT1 expression in esophageal squamous cell carcinoma (ESCC)." (PMID 29855346, 2018). "Indeed, STAT3 itself is capable of interacting with other STATs; STAT1 for example has been demonstrated to exhibit inhibitory effects against STAT3 signaling in a study on esophageal squamous cell carcinoma." (PMID 31555281, 2019). "However, LPA also inhibits EGF-induced activation of signal transducer and activator of transcription 1 (STAT1) in A431 esophageal squamous cell carcinoma cells." (PMID 23467751, 2013). "Inhibition of STAT1, which is regulated by AMPK, promotes the proliferation and metastasis of esophageal squamous cell carcinoma by triggering autophagy both in vitro and in vivo." (PMID 35770085, 2022). "Nonetheless, the biological and clinical significance of STAT1 in esophageal squamous cell carcinomas (ESCC) has not been comprehensively studied." (PMID 25355139, 2014). "Given that CLDN1 is mostly found in the nucleus of esophageal squamous cell carcinoma (ESCC) and has been shown to be abnormally elevated, CLDN1 promotes ESCC growth and metastasis by upregulating the expression of ULK1 via the AMPK/STAT1 signaling pathway." (PMID 36620607, 2022).
head and neck cancer (21 papers, 2008 to 2025). A primary or metastatic malignant neoplasm affecting the head and neck. "Here, we present a 65-year-old woman with a STAT1 GOF variant and severe CMC, who during treatment with anti-PD1 treatment for progressive head and neck cancer had complete regression of severe oral candidiasis." (PMID 41249721, 2025). "Aberrant activation of STAT1 has frequently been found in various cancers, such as head and neck cancer." (PMID 28384236, 2017). "We previously demonstrated an association between an IR-resistant phenotype and overexpression of IFN/STAT1 pathway in head and neck cancer cell lines." (PMID 19503789, 2009). "In the case of solid tumors, Y701 phosphorylation of Stat1 has been detected in breast as well as in head and neck cancers." (PMID 18941537, 2008). "This case demonstrates the unexpected resolution of severe, chronic oral candidiasis in a patient with CMC during treatment of progressive head and neck cancer with pembrolizumab, suggesting a potential, though uncharacterized, beneficial effect of PD-1 blockade in STAT1 GOF CMC." (PMID 41249721, 2025). "In vitro studies showed that EGCG inhibited cisplatin-induced ROS, ERK1/2 and STAT1 activation in UMSCC head and neck cancer cells, but had little effect on cisplatin-induced inhibition of STAT3, Bcl-2 and Bcl-xL levels or the observed increases in cleaved caspase-3." (PMID 28703809, 2017). "Overexpression of EGFR is correlated with PD-L1 expression in head and neck cancers in a JAK2/STAT1-dependent manner, indicating a novel role for JAK2/STAT1 in EGFR-induced immune evasion." (PMID 31775797, 2019). "STAT1, STAT3 and STAT5 proteins are frequently overexpressed in head and neck cancer cell lines." (PMID 23708675, 2013). "Induction of IFNβ post-IR followed by the interplay of IFN-induced proteins (STAT1, ISG15) and cytokines (IL-1β, IL-6, MIF) hints towards IR-induced inflammation contributing to initiation and progression of oral mucositis that affects a majority of head and neck cancer patients." (PMID 37384298, 2023).
non-small cell lung carcinoma (21 papers, 2013 to 2025). A group of at least three distinct histological types of lung cancer, including non-small cell squamous cell carcinoma, adenocarcinoma, and large cell carcinoma. "For instance, lncRNA-HOXC-AS2 regulates TAM polarization through the STAT1/SOCS1 and STAT1/CIITA pathways to promote the progression of non-small cell lung cancer." (PMID 38769475, 2024). "In non-small cell lung cancer, STAT1 as a response factor to IFN-γ promotes PD-L2 expression, this process can be inhibited by STAT1 inhibitor- Fludarabine." (PMID 36522474, 2023). "Recently, the JAK2 inhibitor (SAR302503) role in suppressing STAT1 activation in radioresistant non-small cell lung cancer (NSCLC) cell lines has been recorded." (PMID 33922087, 2021). "IL-10-derived from M2 macrophages enhances the growth potential of non-small cell lung cancer cells (NSCLCs) by activating cancer stemness via janus kinase (JAK)/signal transducer and activator of transcription 1 (STAT1)/nuclear factor-kappa B (NF-kB) pathway." (PMID 32595638, 2020). "Kachroo demonstrated that IL-27 attenuated EMT and the production of pro-angiogenic factors in a STAT1-dominant pathway in human non-small cell lung cancer." (PMID 26932661, 2016). "STAT1 expression levels have been used as part of a five-gene signature for non-small-cell lung cancer survival." (PMID 26841718, 2016). "In addition, TAM-derived IL-10 promotes cancer stem cell (CSC)-like characteristics of non-small cell lung cancer (NSCLC) cells through JAK1/STAT1/NF-κB/Notch1 signaling." (PMID 34722637, 2021). "In non-small-cell lung cancer, IL-10 derived from M2 macrophages promotes cancer stemness through the JAK1/STAT1/NF-κB/Notch1 pathway." (PMID 36838713, 2023). "Through the release of IL-10, M2-type macrophages induce CSC-like properties in non-small cell lung cancer (NSCLC) cells through the activation of JAK1/STAT1/NF-κB/Notch1 signaling." (PMID 36679900, 2022).
parasite infection (21 papers, 2009 to 2026). "In other parasitic infections, such as those caused by helminths, the role of STAT1 is still not completely understood." (PMID 34684235, 2021). "STAT1 has been shown to have a critical role in controlling T. cruzi infection since STAT1 knockout mice are more susceptible to T. cruzi infection than wild-type animals, presenting higher parasitemia in blood and tissues and higher mortality." (PMID 39119291, 2024). "Genetic ablation of STAT1 enhanced mouse survival rates and substantially reduced peripheral parasitemia post-infection and splenic parasite burden." (PMID 41910261, 2026). "As expected, inoculation of either STAT-1−/− or STAT-4−/− mice with WT parasites resulted in high levels of parasitemia and death of 100% of the mice between 15-23 days post-infection (for STAT-1−/−) or 21–62 days for STAT-4−/− mice." (PMID 37185599, 2023). "In the present study, we also find that microglia acquire a neurodegenerative-like DAM signature during T. gondii infection, and that this signature is partially regulated by STAT1 signaling during parasitic infection." (PMID 36067217, 2022). "In various parasite infections, such as those by T. gondii and Schistosoma japonicum, STAT1 and STAT2 are evoked and mediate the immune response." (PMID 34818332, 2021). "Macrophages that are classically activated (M1) through the IFN-γ/STAT1 signaling pathway have a major role in mediating inflammation during microbial and parasitic infections." (PMID 31810203, 2019). "The GFP fusion instead of untagged STAT1 was chosen as substrate, since from our previous experiments it was known that parasite infection resulted in an increased expression of endogenous STAT1." (PMID 25340519, 2014). "The inducible transcription factor Stat1 transmits the immune-protective effects of IFNγ during viral, bacterial and parasitic infections." (PMID 19381261, 2009). "However, initial augmentation in IFN-γ and STAT1 expression levels in this study depicted their effector functionality during early parasitic infection." (PMID 31614626, 2019). "Moreover, TgIST-independent (STAT1-independent) expression of IDO1 fully recovered the IFN-γ-induced growth inhibition by TgIST-sufficient parasite infection." (PMID 30283439, 2018). "Since STAT1-induced transcriptional activation was nevertheless inhibited by parasite infection, we hypothesized a defect in chromatin remodelling and/or activation of the basal transcriptional machinery." (PMID 22275866, 2012). "Parasitemia was positively correlated with IFN-γ, T-BET, RUNX1, and STAT1 and negatively correlated with NFκB factor." (PMID 31614626, 2019). "It is possible that parasite infection down-regulates the IFNγ-induced expression of phosphatases such as suppressor of cytokine signaling 1 (SOCS1), known to negatively regulate STAT1 signaling." (PMID 23527309, 2013). "However, the expression of IL-2, IL-12, IFN-γ, together with that of specific transcriptional factors (STAT1 and STAT4) is suggestive of a Th1-like polarization, induced after parasite infection." (PMID 35632559, 2022). "In contrast, nuclear localization of STAT1 required previous activation of the cells with IFN-γ, and parasite infection did not interfere with this STAT1 redistribution." (PMID 22275866, 2012).
Candida infection (19 papers, 2017 to 2025). "STAT1 gain of function mutations affecting the STAT3/interleukin 17 (IL‐17) pathway causes selective susceptibility to fungal (candida) infections." (PMID 40625894, 2024). "These mutations increase STAT1 responses to IFNα, IFNβ, IFNγ and IL-27, causing repressed development of IL-17 T cells and susceptibility to mucosal Candida infection." (PMID 36012793, 2022). "In a recent paper reviewing the clinical characteristics of 274 patients with GOF STAT1 mutations, candidiasis was found in 98% of patients, and mucocutaneous candidiasis was the most frequently localized form of candidiasis, while 10% of the patients also had a disseminated variety." (PMID 30627128, 2018). "Interestingly, patients with GOF mutations in STAT1 also display defects in the generation of Th17 cells and susceptibility to candida infections demonstrating that balanced STAT1/STAT3 signaling is required for generation of these cells." (PMID 29472924, 2018). "This case is presented to prompt clinicians to consider STAT1 GOF mutations in the differential diagnosis of patients with chronic Candidiasis and recurrent infections with multiple organisms, since these mutations are responsible for nearly half of CMC cases reported." (PMID 29259832, 2017). "STAT1 GOF variants are associated with increased PD-L1 expression, which suppresses Th17 differentiation, a key immune response against Candida infections." (PMID 41249721, 2025). "Type I and I IFNs, which signal via STAT1, inhibit Th17 cells; thus, enhancement of IFN-induced STAT1 signaling has been attributed to impaired IL-17 production and susceptibility to Candida infection." (PMID 40552831, 2025). "Susceptibility to recurrent Candida infection in CMC is caused by various host genetic mutations, the most common being STAT1 gain of function mutations." (PMID 36012793, 2022). "Patient 2 had a STAT1 mutation impairing the IFN-γ-IL-12/23 circuit, thereby increasing susceptibility to mycobacterial and Candida infections." (PMID 28623282, 2017). "En el presente informe, se identificó una variante patogénica de novo en el gen STAT1, con aumento de la función, en un paciente con candidiasis mucocutánea crónica, infección por bacilo de Calmette-Guérin, tuberculosis pulmonar, herpes zóster y rosácea." (PMID 39836847, 2024). "In patient P2, who manifested a GOF mutation in the STAT1 gene and severe CMC since the age of 8 months with very poor responses to many pharmacological treatments, the severe oral Candida infection (resistant to voriconazole) was cleared to a great extent with only the IV IgG mouthwash treatment." (PMID 30627128, 2018). "Indeed, candida infections have been widely reported in association with SLE mucositis, even if we cannot know if any of the cases described in the literature were actually due to STAT1 GOF." (PMID 33971891, 2021).